ESR1 (estrogen receptor 1)
Diseases named in the same sentence as ESR1 in open-access papers (continued):
Sharing a sentence is not in itself a finding about the gene and the disease.
tumor (continued). "Fulvestrant in combination with palbociclib showed a partial response to the relevant patient’s tumor harboring the ESR1 mutation, and CCND1 amplification was found in the PDX model." (PMID 33407601, 2021). "This is a relatively high percentage in contrast to studies using ddPCR or NGS (next generation sequencing) that have shown undetectable or extremely low allele frequencies of ESR1 mutations in primary tumours." (PMID 33535614, 2021). "A previous study from the BOLERO trial, using NGS, found ESR1 mutations in 3% of the primary tumours (6/183)." (PMID 33535614, 2021). "We conducted a prospective study in a cohort of HR+/HER2- mBC patients to assess the concordance of ESR1 mutation evaluated on matched tumor tissue samples from a metastatic lesion and ctDNA from plasma." (PMID 33777770, 2021). "ESR1 expression level was negatively associated with tumor purity (r= – 0.141, P= 1.88e−02), B cells (r = 0.141, P= 1.81e−02), CD4 + T cells (r = 0.185, P= 2.03e−03), and macrophages (r = 0.143, P = 1.76e−02)." (PMID 34784845, 2021). "Our total ESR1 mutation rate, considering cases showing a mutation on tumor tissue and/or ctDNA over the total, was 21% (9/43)." (PMID 33777770, 2021). "The detection of ESR1 mutations in the primary tumours also highlights the sensitivity of the assay." (PMID 34499316, 2021). "We identified the following ESR1 mutations in six of 43 patients (14%) on DNA extracted from tumor biopsies: Y537S (one subject), Y537N (one subject) E380Q (two subjects), D538G (two subjects)." (PMID 33777770, 2021). "Whole exome sequencing (WES) was used to detect the tumor samples and showed the peritoneal metastatic lesions had acquired ESR1 and PI3KCA mutations, potentially explaining the mechanism of endocrine therapy resistance." (PMID 34690920, 2021). "DFS and DRFS were significantly shorter (p = 0.04 and p = 0.017, respectively) in patients that had ESR1 mutations (> 1%) in their loco-regional recurrence tumor." (PMID 32014063, 2020). "Y537N and Y537S were detected in 13.89% of biopsies from patients with hormone resistant tumours and accounted for over half of all detected ESR1 mutations." (PMID 32932819, 2020). "The most established cell-free tumor DNA (ctDNA) factors associated with ET resistance [ESR1 and phosphatidylinositol-4,5-bisphosphate 3-kinase, catalytic subunit alpha (PIK3CA) mutations] were assessed through next-generation sequencing." (PMID 33072577, 2020). "In this study, ESR1 mutations were observed in 37% of baseline tumor samples: these mutations are clearly enriched in luminal A (72%) and PIK3CA-mutant (60%) patients." (PMID 32210163, 2020). "Studies on ESR1 mutations in circulating plasma tumor DNA and for evaluating the prognostic and predictive values of ESR1 circulating mutations employed Bio-Rad ddPCR systems." (PMID 33233830, 2020). "After further adjust the effect of tumor‐related pathological factors, the ESR1 mRNA expression independent associated with survival in LIHC and MESO and ESR2 independent associated with survival in BRCA, KICH, KIRP, LGG, and PAAD." (PMID 32536040, 2020). "Therapies that modulate the mutant receptor are in clinical trials, and ESR1 mutations in circulating tumor DNA are a promising biomarker for disease progression." (PMID 32374727, 2020). "The application of ddPCR to circulating tumor DNA for detecting ESR1 mutations and monitoring treatment response or progression is still being investigated." (PMID 33233830, 2020). "Studies have shown that estrogen receptor 1 (ESR1) mutations are known resistance mechanisms of tumor cells to AI or gonadotropin-releasing hormone analogues." (PMID 33292625, 2020). "In further support of their prognostic role, baseline tumor ESR1 mutation rates were found to be lower among long-term responders in both PALOMA-3 trial arms." (PMID 31795152, 2019). "Gene expression of 33 genes was significantly different in the progression sample between ESR1 wild-type and the ten-mutated tumours." (PMID 30563991, 2019).
tumor (continued). "Treatment resistance frequently arises when tumor cells develop constitutive activity in the estrogen receptor through mutation of its gene, ESR1." (PMID 30925887, 2019). "The co-association of the high ERG expression and high proliferation genes in the ESR1-mutated tumours is consistent with the tumour progression being at least partly driven by the mutations." (PMID 30563991, 2019). "This study demonstrates the utility of the enhanced-ice-COLD-PCR approach for simplifying and improving the detection of ESR1 tumor mutations in liquid biopsies." (PMID 29531247, 2018). "In the 2 patients (S-28 and S-26) who showed a wildtype ESR1 according to biopsies but a mutated gene in cfDNAs, the differences were related to the heterogeneity of the tumor sample, or the evolution of the neoplasm over time." (PMID 29531247, 2018). "With the aim of establishing a sensitive method for the detection of ESR1 mutations in cfDNA, we identified ESR1 mutant alleles by investigating tumor tissue samples from a cohort of 40 patients with metastatic BC." (PMID 29531247, 2018). "Given the concordance between ddPCR in blood vs. tumor specimens, we next proceeded to evaluate the frequencies of ESR1 mutations and PIK3CA mutations in the entire cohort (n = 155)." (PMID 30083595, 2018). "ESR1 mutations and mRNA splice variants are likely to emerge during treatment and can therefore only be observed in tumor cells obtained during or after treatment." (PMID 29063679, 2018). "CTCs count and ESR1/PIK3CA mutations in circulating tumor DNA were performed and correlated with TK1 activity." (PMID 29662653, 2018). "Early studies reported ESR1 mutations in tumor samples obtained from different organ sites, including lymph nodes, skin, lung, and liver, suggesting that these mutations do not display specific organotropism." (PMID 28361033, 2017). "After 20 years, the presence of the E380Q ESR1 mutation came to be reported in both tumor tissue DNA (ttDNA) and plasma cfDNA." (PMID 29166868, 2017). "We screened a total of 62 patients (66 tumor tissues and 69 plasma cell-free DNA (cfDNA)) to detect ESR1 mutations (E380Q, Y537S, Y537N, Y537C, and D538G) using droplet-digital polymerase chain reaction." (PMID 29166868, 2017). "We will explore the prospects for analysis of ESR1 mutational status as a prognostic and predictive biomarker as well as the development of therapeutic strategies targeting ESR1-mutated tumor cells." (PMID 28361033, 2017). "Initial studies describing ESR1 mutations were performed in metastatic tumor samples from retrospective cohorts and clinical trials." (PMID 28361033, 2017). "Numerous recent reports have demonstrated the detection of mutant ESR1 DNA alleles as tumor-specific biomarkers in cell-free DNA (cfDNA) from blood." (PMID 28361033, 2017). "We also detected an ESR1 mutation (E380Q) in the tumor biopsy that was confirmed at low clonal fractions in cfDNA." (PMID 29109393, 2017). "Cell-line-dependent effects have previously been described for the study of other mutations, and future studies need to address if and how this relates to inter-tumor heterogeneity with respect to the effects of ESR1 mutation." (PMID 28535794, 2017). "We observed five cases with multiple ESR1 LBD mutations in the same tumor: three had double ESR1 mutations; Y537S/E380Q, Y37S/Y537C, and Y537S/D538G, and two had triple ESR1 mutations; Y537S/Y537N/D538G." (PMID 29166868, 2017). "In this study we were able to analyze, cfDNA ESR1 mutations in serial samples from tumor tissues of 14 out of the total of 42 MBC patients." (PMID 27102299, 2016). "Similar to ESR1, a slightly higher proportion of patients with luminal A tumours had PIK3CA mutations in ctDNA compared with patients with luminal B tumours (44%, 44/100 versus 38%, 17/45)." (PMID 27174596, 2016).
tumor (continued). "Since 2015, several studies have shown that ESR1 mutation detection in circulating tumour DNA (ctDNA) was clinically relevant and correlated with mutational status on metastasis." (PMID 27801670, 2016). "This notion was stressed by the recent discovery of specific ESR1 (the gene that encodes for ERα) mutations in relapsed tumor tissue, after having received adjuvant tamoxifen or aromatase inhibitor therapy." (PMID 27129152, 2016). "It would, therefore, be of interest in future studies to combine 18F-FES-PET/CT with analysis of ESR1 gene amplification and mutation in tumour biopsies, in order potentially to improve the selection of patients for oestrogen therapy." (PMID 26091705, 2015). "The observed interaction between ERE-associated SNPs and either the ESR1 SNP or the ER status of the tumor also provides evidence for the breast tumorigenic relevance of these ERE-associated SNPs." (PMID 25298020, 2014). "The applied iatrogenic selection leads to survival of tumor cells with acquired resistance, one example being ESR1 mutations under antihormonal therapy." (PMID 25358515, 2014). "Based on commonality in gene expression, we successfully defined an “835 prognosis classifier” subset as a prognostic classifier that is more powerful at prognosis prediction than most tumor risk factors (e.g. histological grade, ESR1) in current use." (PMID 23565194, 2013). "ESR1 is known to play a very important role in cancer, and previous research found that ESR1 methylation is associated with concurrent methylation of a group of tumor suppressors." (PMID 23320390, 2012). "DC-SCRIPT levels were positively associated with tumor grade and ESR1, PGR, and ESR2 steroid hormone receptor expression level and negatively associated with invasive epithelial tumor cell content and tumor size." (PMID 21122099, 2010). "ESR1 encodes the ERα, and its expression in tumour cells is a prognostic and predictive factor that is routinely used when making decisions on hormonal therapy." (PMID 19094228, 2008). "Additionally, BC_cells3, marked by the expression of ESR1, serves as the primary tumor cell subtype associated with BC-BoM." (PMID 41362730, 2026). "Additionally, circulating tumor DNA (ctDNA) analysis, interpreted through AI algorithms, has enabled earlier detection of ESR1 mutations and prediction of endocrine resistance." (PMID 40989687, 2025). "Studies have shown that ESR1 knockout in mouse models increases susceptibility to liver tumorigenesis, while its activation through estrogen signaling suppresses tumor growth." (PMID 41048345, 2025). "We hypothesise that extended aromatase inhibition may further increase the likelihood of developing ESR1 mutations in luminal B tumours." (PMID 39921934, 2025). "In this study, we investigated whether analysis of CTCs and circulating tumor DNA (ctDNA) provide similar or complementary information for the analysis of ESR1 mutations." (PMID 39754401, 2025). "Using multiplex‐ddPCR and identical blood draws, we investigated whether circulating tumor cells (CTCs) and cfDNA provide similar or complementary information for ESR1 mutations." (PMID 39754401, 2025). "Notably, ERD-3111 demonstrated superior bioavailability and achieved significant tumor regression and complete growth inhibition in wild-type and two clinically relevant ESR1-mutated (Y537S and D538G) MCF-7 xenograft models, outperforming ARV-471." (PMID 40641933, 2025). "Based on our findings, CTCs provide valuable information about the tumor's ESR1 mutation status." (PMID 39754401, 2025). "For example, relevant studies have found that the variants rs12913832 in HERC2, rs3798577 in ESR1, and rs183471242 on chromosome 11 are linked to both MM risk and tumour thickness, suggesting that germline genetic variation plays a crucial role in disease development and progression." (PMID 40305358, 2025). "Interestingly, recent studies showed that ESR1 mutations occur more frequently in luminal B versus A tumours." (PMID 39921934, 2025).
tumor (continued). "Our objectives were to quantify circulating tumour DNA (ctDNA) levels, assess ctDNA dynamics, and explore how ctDNA ESR1 mutations (ctESR1m) may influence treatment response, as their impact on Irosustat efficacy remains unclear." (PMID 41364261, 2025). "Additionally, tumor tissues from patients classified as Normal-like were significantly associated with AR/ESR1 ≥ 2.0, compared to Luminal A tumors (Odds ratio: 0.371; 95% CI: 0.145–0.949; p = 0.039)." (PMID 40593140, 2025). "The retrospective design and the treatment period also precluded the collection of data on relevant tumor genomic alterations, such as PIK3CA, AKT, PTEN, and ESR1, which limited our ability to assess the potential association between these tumor mutations and treatment outcomes." (PMID 39982725, 2025). "Functional verification via gene overexpression elucidated distinct mechanisms underlying the action of FF: ESR1 acts as a tumor suppressor by enhancing FF’s anti-proliferative effect; conversely, c-Jun and MMP9 exhibit pro-cancer characteristics by counteracting FF’s activity." (PMID 40630198, 2025). "Furthermore, the content of ESR1 mutations in ctDNA is often higher than that in matched tumor tissues." (PMID 39544302, 2024). "Our findings revealed that high MET/ESR1 coexpression was associated with favorable clinicopathologic tumor features such as greater age at diagnosis, lower NPI scores, low-grade carcinoma, hormone receptor positivity, HER2-negative status, and luminal subtype." (PMID 39742369, 2024). "Camizestrant is an oral SERD that suppresses tumor growth in patients with ESR1 mutation." (PMID 39063972, 2024). "Furthermore, in two different PDX models harboring ESR1 mutations, combination treatment with elacestrant and palbociclib effectively stopped tumor growth." (PMID 39767607, 2024). "The goal of such a vaccine strategy would be to educate CD8+ T cells to identify and eliminate circulating tumor cells that may contain ESR1 mutations which could potentially extend the length of time patients respond to endocrine therapy." (PMID 38335301, 2024). "Indeed, clinical data suggest reduced efficacy of aromatase inhibitors compared with fulvestrant in patients who have ESR1 mutations in the tumor or circulating tumor DNA (ctDNA)." (PMID 39767607, 2024). "In our series, EV-DNA might provide a more efficient tumor source than ctDNA to evaluate the prognostic role of ESR1 mutations." (PMID 39684756, 2024). "During first-line treatment with a CDK4/6i + ET, the early onset of ESR1 mutations detected in circulating tumor DNA (ctDNA) could direct a switch strategy including modification of the endocrine backbone." (PMID 38930141, 2024). "In tumor cells treated with tamoxifen, abundant lncRNA transcripts of ERs mediate the activating mutations for crucial genes of the genome stabilizer circuit; such as ESR1, BRCA1, and CYP19A." (PMID 38672654, 2024). "Notably, the somatic NGS panel can offer other information with clinical relevance, such as the presence of mutations in BRCA1, BRCA2, PALB2, ERBB2, and ESR1, in addition to molecular changes that can be treated with tumor-agnostic therapies." (PMID 38952553, 2024). "The ability to monitor ESR1 mutations through serial ctDNA testing holds great promise in improving patient outcomes by enabling clinicians to adjust treatment regimens in response to real-time changes in the tumor's genetic profile." (PMID 40027941, 2024).